LINC01011 (long independently transcribed non-coding RNA 1011)
Synonyms: CISAL; DKFZp686I15217
Gene: Long non-coding RNA gene on chromosome 6 (2,987,967 to 2,991,173, forward strand). Ensembl gene ENSG00000244041.
Diseases named in the same sentence as LINC01011 in open-access papers:
LINC01011 is named in the same sentence as 8 diseases in open-access papers, as found by Europe PMC text mining. Sharing a sentence is not in itself a finding about the gene and the disease. The quoted sentences say what the papers report.
colon cancer (1 paper, 2022). "A total of 709 autophagy-related genes were identified in colon cancer tissues, and 11 autophagy-related lncRNAs (AL138756.1, LINC01063, CD27-AS1, LINC00957, EIF3J-DT, LINC02474, SNHG16, AC105219.1, AC068580.3, LINC02381, and LINC01011) were finally selected and set as prognosis-related lncRNAs." (PMID 36035142, 2022).
cancer (2 papers, 2020 to 2022). A tumor composed of atypical neoplastic, often pleomorphic cells that invade other tissues. "Among the 11 autophagy-related lncRNAs, 8 lncRNAs were already verified to be associated with cancer development: LINC01063, CD27-AS1, LINC00957, EIF3J-DT, LINC02474, SNHG16, LINC02381, and LINC01011." (PMID 36035142, 2022).
LINC01011 also shares sentences with these, for which no sentence is quoted: bladder carcinoma (1 paper); glioma (1); lung adenocarcinoma (1); ovarian carcinoma (1); pancreatic adenocarcinoma (1); tumor (1).